ZC3H11B (zinc finger CCCH-type containing 11B)
Description:
May play a role in mRNA transport.
Synonyms: ZC3HDC11B
Gene: Protein-coding gene on chromosome 1 (219,608,012 to 219,613,105, reverse strand). Ensembl gene ENSG00000215817.
Subcellular location (Human Protein Atlas): Nuclear speckles
Gene Ontology:
Molecular function: metal ion binding
Biological process: poly(A)+ mRNA export from nucleus
Genetic constraint (gnomAD): Loss-of-function variants: 1 observed, 6.35 expected, observed/expected ratio (o/e) 0.16, 90% interval 0.055 to 0.75. That is too few expected variants to judge how well the gene tolerates losing a copy. Missense variants: 54 observed, 114.33 expected, observed/expected ratio (o/e) 0.47, 90% interval 0.38 to 0.59. Synonymous variants: 23 observed, 41.18 expected, observed/expected ratio (o/e) 0.56, 90% interval 0.4 to 0.79.
Homologues: Orthologues: macaque ZC3H11A (93% identical), dog ZC3H11A (85% identical), mouse Zc3h11a (74% identical), tropical clawed frog zc3h11a (38% identical), zebrafish zc3h11a (35% identical). Paralogues in human: ZC3H11C (99% identical), ZC3H11A (93% identical), ZC3H11D (11% identical).
Diseases named in the same sentence as ZC3H11B in open-access papers:
ZC3H11B is named in the same sentence as 8 diseases in open-access papers, as found by Europe PMC text mining. Sharing a sentence is not in itself a finding about the gene and the disease. The quoted sentences say what the papers report.
myopia (5 papers, 2012 to 2024). "ZC3H11B has also been associated with myopia endophenotypes, including axial length, refractive error, and corneal astigmatism." (PMID 36584111, 2022). "Lastly, our group investigated the associations with myopia progression and PRSs of SNPs in six genes—ZC3H11B, ZFHX1B, KCNQ5, SNTB1, GJD2 and MET—among Chinese children in Hong Kong." (PMID 35327754, 2022). "The minor C allele of rs4373767 on ZC3H11B demonstrated a protective effect against high myopia and elongated axial length." (PMID 35327754, 2022). "Our own study on Chinese subjects in Hong Kong confirmed ZC3H11B as a susceptibility gene for both high and extreme myopia, as well as ZFHX1B and SNTB as susceptibility genes for extreme myopia." (PMID 35327754, 2022). "Markers near the protein coding gene ZC3H11B (zinc finger CCCH-type containing 11B) on chromosome 1 (1q41) have previously demonstrated association with pathological (high) myopia in Asian ancestry cohorts and with axial length in both European and Asian ancestry individuals." (PMID 30306274, 2018). "It is thought that accelerated connective tissue remodelling of the posterior sclera leads to axial elongation, a key feature of myopia, thereby implicating ZC3H11B in a number of suspected connective tissue diseases." (PMID 36584111, 2022). "Researchers indicate that PAX6 rs644242, ZC3H11B rs4373767 and BICC1 rs7084402, VIPR2 rs885863 and rs6979985, ZMAT4 rs7829127, TNKS rs4840437 and rs6989782, PDGFRA rs2114039, SOX2 rs4575941, FGF10 rs339501, rs2973644, and rs 79002828 are associated with severe myopia (moderate and extreme myopia)." (PMID 38660258, 2024). "Although the function of the ZC3H11B in humans is presently unknown, the implicated role of the murine gene ZC3H11A (conserved gene of ZC3H11B in mouse) in myopia development is in keeping with previous findings that several zinc finger proteins are involved in myopia." (PMID 22685421, 2012). "In light of this, the observation that ZC3H11B is abundantly expressed in retina and sclera, together with the significant down-regulation of the coding counterpart ZC3H11A in myopic mice eyes, suggests it may promote or inhibit the transcription of ocular growth genes vital in myopia development." (PMID 22685421, 2012).
Corneal astigmatism (2 papers, 2018 to 2022). "Single marker-based association tests for corneal astigmatism identified four genome-wide significant loci (P < 5 × 10−8) near the genes ZC3H11B (1q41), LINC00340 (6p22.3), HERC2/OCA2 (15q13.1) and NPLOC4/TSPAN10 (17q25.3)." (PMID 30306274, 2018).
Astigmatism (1 paper, 2025). A type of refraction error associated with abnormal curvatures on the anterior and/or posterior surface of the cornea. "SNPs near other loci, including RPS6KC1 rs12144639, ZC3H11B rs7525202, TRAF3IP1 rs77008212, and CASC15 rs4712652, were nominally associated with various types and components of astigmatism, as well as CR." (PMID 41320768, 2025).
Hernia (1 paper, 2022). "Five biologically relevant loci were discovered on individual hernia analyses to confer shared susceptibility to multiple hernia phenotypes including 1q41 (ZC3H11B), 2p16.1 (EFEMP1), 6p22.1 (MHC region), 7q33 (CALD1) and 11p13 (WT1)." (PMID 36584111, 2022). "The strongest association was observed at 2p16.1 (EFEMP1), closely followed by 1q41 (ZC3H11B) and 11p13 (WT1) which were all identified as shared susceptibility loci on analysis of the individual hernia cohorts." (PMID 36584111, 2022).
pelvic organ prolapse (1 paper, 2022). Abnormal descent of a pelvic organ resulting in the protrusion of the organ beyond its normal anatomical confines. "Additionally, EFEMP1 has recently been implicated in conferring susceptibility to pelvic organ prolapse and intriguingly is also associated with anthropometric measures of height and abdominal circumference, which have also been associated with ZC3H11B." (PMID 36584111, 2022).
ZC3H11B also shares sentences with these, for which no sentence is quoted: connective tissue diseases (1 paper); glaucoma (1); ventral hernia (1).